CD44 (CD44 molecule (IN blood group))
Diseases named in the same sentence as CD44 in open-access papers (continued):
Sharing a sentence is not in itself a finding about the gene and the disease.
infection (continued). "In order to identify the phenotype of CD8+ T cells generated during this infection/cure under CQ cover regimen, splenocytes and peripheral blood from mice three weeks post last inoculation for the presence of CD8+, CD3+, CD11a, CD127, CD27, KLRG1, CD44 and CD62L cells by flow cytometry was analysed." (PMID 24620841, 2014). "In order to assess the nature of the T cells recruited to the site of infection, FP granuloma lymphocyte populations from each strain were stimulated with various M. leprae crude and purified antigens in vitro and evaluated by flow cytometry for IFN-γ production by CD4+CD44+ and CD8+CD44+ cells." (PMID 25210773, 2014). "The results revealed that the miR-200c overexpression in the tumors led to a marked reduction of ZEB1 mRNA, Vimentin mRNA and the protein expressions compared with the CD44+CD117+CSCs with lentivirus mock and with the CD44+CD117+CSCs without lentivirus infection." (PMID 23842108, 2013). "However, as activated/effector CD4+ and CD8+ T cells (defined by CD44 and CD62L expression) appeared in elevated numbers, it is possible that the remaining anti-CD25 antibodies were still blocking CD25 epitopes on T cells at week 2 of infection." (PMID 23226464, 2012). "In mice that were primarily infected with Lm and L.inn::vgc, the expression of CD44 was upregulated on CD8+ T-cells 5 days post-challenge infection with the wild type Lm (2×103) while primary infection with L.inn did not lead to a significant change in CD44 expression pattern." (PMID 22536395, 2012). "Results were consistent with the in vitro findings, which showed that E44 infection could increase the expression of ICAM-1 and CD44 in wildtype mice, and that nicotine could amplify E44-induced expression of these two adhesion molecules in the wildtype animals." (PMID 21966399, 2011). "Taken together, our data suggests that IL-7 and IL-15 have overlapping roles in mediating up-regulation of Bcl-2 and CD127 on antigen-specific CD8+ T cells and that differential CD127 expression does not impede CD44 expression or effector functions during acute phase infection." (PMID 20520779, 2010). "The significant differences between the groups in the CD44 and OPN status suggested that vaccination may enhance certain immune pathways, potentially offering greater protection or a more vigilant immune state compared to natural infection or the unvaccinated state." (PMID 39337033, 2024). "In addition to elevated levels of CD44, Tregs in IFNARflf/fl x Foxp3YFP-Cre mice also expressed higher percentages of other activation markers, including Ki-67+, ICOS+ and TIGIT+, consistent with an activated phenotype and greater degree of proliferation at day 5 post Armstrong infection." (PMID 29672594, 2018). "Since the modest increase in the density of CD44 alone (~10%) could not account for the large (2-fold) changes in the rolling parameters of infected cells; we investigated the changes in the distribution of CD44 on cell surface due to infection." (PMID 26785849, 2016). "Endocytosis-related proteins CD44, Rab5, Rab7, and LAMP2 were increased after infection, while the level of Cathepsin L did not change." (PMID 34163451, 2021). "Nearly 67% of Tcyt cells in noninoculated middle ear fluid were effector Tcyt (CD44+ CD62L−) cells, and the percentages of these gradually increased up to 90% in the later days of NTHi infection." (PMID 31548315, 2019). "CD44-negative cells were reduced in their transcriptional response to interferon gamma (IFN-γ), viral DNA or infection with L. monocytogenes." (PMID 30540779, 2018). "To investigate the changes in the earliest thymocyte precursors gated as DN population lacking CD4 and CD8, we analyzed the CD44 and CD25 expression profiles upon infection." (PMID 28091621, 2017). "We also observed that infection did not appreciably alter the expression levels of CD15, CD62L and CD162 from the already low levels and increased CD44 expression levels only modestly (~10%)." (PMID 26785849, 2016).
infection (continued). "Conversely, a significant frequency of CD44+ CD62L− cells, particularly in the spleen, did not express CD49d and CD11a during infection." (PMID 26459508, 2016). "At 5 days post-infection, Granzyme B+CD4+ T cells up-regulated the adhesion molecule CD44, but expressed neither the co-stimulatory receptor CD27 nor the memory T cell marker CD127 (a subunit of interleukin-7 receptor-α)." (PMID 24367519, 2013). "Further indication of OT-I cell activation during infection is provided by the down-regulation of CD62L and up-regulation of CD44 and CD69 (not shown)." (PMID 21829561, 2011). "While characterizing the activation status of CD8+ T cell, we found at least a 10-fold increase in the effector phenotype (CD44+) and a concomitant decrease in the naïve phenotype (CD62L+) that was evident on the 8th day of infection and with no apparent difference between WT and Cd47−/− mice." (PMID 36105746, 2022). "Of these, CD44, KDM1B, FKBP4, TEF, SYT4, SATB1 and PLCD1 are reported to be involved in the inflammatory reaction; for the remaining ten genes, there have been no reports concerning inflammation or infection." (PMID 34046191, 2021). "We observed that regardless of the infection state in SFB colonized eSPF mice, within small intestinal LPLs nearly 100% of IL-17A+IL-22- cells expressed CD44+ and lacked CD62L expression with around 70% of them expressing CCR6, which is in contrast to IL-17A-IL-22- cells." (PMID 34566952, 2021). "We tested this bystander potential in an LM-OVA model, where mice were sacrificed 4 days after infection, such that no OVA-specific cells could be detected, and bystander cells were gated based on CD44 and NKG2D expression as in previous reports." (PMID 33897691, 2021). "The numbers of intracerebral OT‐I CD44+ cells in the brains of drug‐treated mice on day 7 of infection were significantly lower than in non‐drug‐treated mice experiencing fatal ECM, whereas the number of splenic OT‐I CD44+ cells on day 7 of infection was not significantly affected by drug treatment." (PMID 34407221, 2021). "However, the CD4+CD44+IFN-γ+ T-cell (R = 0.6789, p < 0.0001) responses to ESAT-6 correlated negatively with bacterial load post-infection, but not pre-infection." (PMID 32545304, 2020). "On day 5 post-infection, the vast majority of antigen-specific IFN-γ+ T cells in the ear were derived from the CD44+CD4+T-bet+CD62L− effector population that had not divided, while very few IFN-γ+CD44+CD4+T-bet+CD62L+ T cells were found, and those that were found had undergone proliferation." (PMID 29922288, 2018). "To determine whether MCMV spread requires CD44 engagement, we gave mice i.n. luciferase+ MCMV, treated them with a CD44-blocking MAb (IM7) or did not treat them with a CD44-blocking MAb, and quantified infection by light emission from dissected organs." (PMID 28974616, 2017). "However, PRH overexpression did not alter expression of CD44 and CD24 marker proteins in cells prior to mammosphere formation at 48 h post-infection as measured using flow cytometry." (PMID 28604763, 2017). "Remarkably, a proportion of transferred CD44+CD62L−Ly6C+ cells, which do not need to undergo proliferation to mediate effector function, also underwent proliferation in infection-matched recipients and maintained Ly6C and Tbet co-expression in both the dLN and spleen." (PMID 25473946, 2014). "Although the absolute numbers of all cell types analyzed considerably increased upon infection, we did not observe any change in relative numbers of CD8+ or CD4+ T lymphocytes, even though there were minor shifts in their CD44 and CD62L expressing subpopulations." (PMID 25919005, 2014). "Thus, the kinetics of CD44 and CD62L expression and IFN-γ production each reveal delayed T cell activation early after infection, not peaking until weeks 3 to 4, that is followed by more sustained T cell activation thereafter." (PMID 20714351, 2010).
infection (continued). "Nevertheless, CXCR6 was highly expressed in CD4+ TIA cells from memory mice but also in NKG2D+CD4+CD44+ T cells from control mice, which could be stimulated to produce IFN-γ in vitro, but were not recruited to the site of infection in vivo, hinting toward alternative recruitment mechanisms." (PMID 38838013, 2024). "However, in the presence of FRCs, which can capture HIV-1 through HA-mediated interactions between CD44 on their surface and virion-incorporated CD44, unlike CD4+ T cells, HIV-1 dissemination may be efficiently mediated though trans-infection in SLOs." (PMID 34696365, 2021). "In this light, we measured CD25, CD44, and ICOS as markers of activation, which might correlate with Helios expression, but found this not to be the case either at steady state or following infection." (PMID 24185641, 2014). "In the absence of PMNs, at 8 days of infection, there is an increase in the proportion of other leukocytes such as CD4+ and CD8+ T cells with up-regulated expression of the effector/memory-like activation surface marker glycoprotein CD44 in Brucella infected mice." (PMID 23458832, 2013). "The trafficking of TLR9 in JIMT-1 CD44-/CD24- non-CIC population showed a similar pattern as ArLa non-CIC: The receptor was found in the ER and at low levels in endosomes in non-infected cells and upon infection TLR9 was upregulated and trafficked from the ER to the endosomes." (PMID 21079774, 2010).
adenocarcinoma (40 papers, 2008 to 2026). A common cancer characterized by the presence of malignant glandular cells. "Cells tend to lose the ability of CD44 expression as they progress from well-differentiated adenocarcinoma to poorly differentiated adenocarcinoma." (PMID 37461792, 2023). "The predominant localization of CD44 in the nuclei of luminal normal epithelial prostatic cells and adenocarcinoma cells suggests that it is the cleaved product of CD44, i.e., “CD44-ICD”." (PMID 33062960, 2020). "Since many BC cells and BCSCs are characterized by high expression of CD44 while others show low expression, we decided to select MDA-MB-231 as CD44+ and adenocarcinoma MCF-7 as CD44− cells, respectively, to study receptor-mediated endocytosis of NPs." (PMID 31979218, 2020). "Although the lumen is filled with adenocarcinoma cells, few cells in the lumen displayed the distribution of CD44-ICD." (PMID 33062960, 2020). "A549 (adenocarcinoma) cell population was sorted via flow cytometry according to high (CD44 Bright) and low CD44 (CD44 Dim) expression." (PMID 29047224, 2017). "We therefore analyzed LGR5 ISH and Ki67, KRT20 and CD44 IHC in 23 adenocarcinomas of all stages (pT1: n = 9, pT2: n = 3, pT3: n = 7, pT4: n = 4)." (PMID 25728748, 2015). "We analyzed the level of Ki67, KRT20 and CD44 expression in the adenocarcinomas (n = 23) by using a four grade semi-quantitative scoring system with 0 representing no staining and 3 representing the strongest staining." (PMID 25728748, 2015). "Our data as well as those from several studies have shown a significantly more frequent CD44 expression in squamous compared with adenocarcinoma histology." (PMID 21124918, 2010). "Here we demonstrate that human ESA+CD44+ CoCSC generate adenocarcinomas that resemble parental tumors in both their phenotype and histology upon serial transplant in a xenograft setting and are enriched in tumors following classical chemotherapeutic regimens intended to shrink tumors." (PMID 18560594, 2008). "Our study is the only one so far to evaluate the correlation of the markers ALDH1, BMI-1, CD44, Nanog, and SOX2 with survival-rates and clinicopathological data in adenocarcinoma of the major salivary glands." (PMID 33009929, 2021). "Second, we determined the expression levels of CD44-ICD in tissue microarray sections containing normal prostatic tissues and stage 1-4 adenocarcinoma tissue." (PMID 33062960, 2020). "CD44-ICD staining was perinuclear and predominantly in the nuclear regions of adenocarcinoma cells as well as in the nuclei of some basal and stromal cells." (PMID 33062960, 2020). "Of note, higher expression of CSC markers and key stem pathways was also found on UWG02CTC versus UWG01CTC, despite ALDH1, CD44, and CD133 reported as CSC markers in both adenocarcinomas and high grade neuroendocrine tumours." (PMID 31953491, 2020). "Class B cell lines (CLB) are adenocarcinomas exhibiting a pure epithelial morphology and the EpCAM+CD24+CD44+CD133+ phenotype." (PMID 26158412, 2015). "The data suggest that SCC express higher levels (4+/3+) of CD44 and ALDH than adenocarcinoma, and co localization of these markers (the CD44hi/ALDHhi surface phenotype) is also easier to identify in SCC (n = 5/7) than in adenocarcinoma (n = 1/12)." (PMID 24019906, 2013). "Only 53 % of tumors with co-expression of MMP-14 and CD44 were of serous histology versus 72 % in the no/single-expression group; clear cell histology was 16 % versus 8 % in the co-expression group; and unspecified histology was 10 % versus 4 % in the adenocarcinoma group." (PMID 27590006, 2016). "Regarding the results of our study and the literature, the CSCs ALDH1, BMI-1, CD44, Nanog, and SOX2 seem not to serve as reliable prognostic parameters in adenocarcinomas of the salivary glands." (PMID 33009929, 2021).
adenocarcinoma (continued). "Recapitulating the results of our study in conjunction with the literature, the CSCs ALDH1, BMI-1, CD44, Nanog, and SOX2 do not seem to serve as reliable novel prognostic parameters in the treatment of adenocarcinoma of the salivary glands." (PMID 33009929, 2021). "Recapitulating the results of our study in conjunction with data in the literature, the CSCs ALDH1, BMI-1, CD44, Nanog, and SOX2 do not seem to serve as reliable prognostic parameters in the treatment of adenocarcinoma of the salivary glands." (PMID 33009929, 2021).
bacterial infection (14 papers, 2014 to 2024). "As expected, we find elevated expression levels of the inflammation response to bacterial infection marker CD44 in the LPS-treated cells 57,67,68." (PMID 38977691, 2024). "In T lymphocytes, CD44 participates in hematopoiesis, inflammation, and response to bacterial infection." (PMID 33971369, 2021). "We show that CD4+ T-cell-dependent antigen presentation generates central memory CD8+ T cells (CD44+CD62LhighCCR7+) in vivo in a natural repertoire environment, in the course of a bacterial infection." (PMID 29147022, 2017). "Another interesting question concerns the memory function of γδ T cells during MCMV infection, as recently described for CD44+CD27− γδ T cells in mouse models of bacterial infections." (PMID 25747674, 2015). "Consequently, HASS-TCS is internalized into cells via CD44-mediated endocytosis in the context of intracellular bacterial infection, thereby facilitating a series of antibacterial processes." (PMID 39770059, 2024). "However, further studies are required to determine the exact role of CD44 ICD in viral/bacterial infections in vivo." (PMID 37894408, 2023). "Therefore, the increased expression of miR-4535, a target gene of CD44, may represent a disruption in the defense mechanism against bacterial infection in utero owing to the decreased expression of its target gene, CD44." (PMID 39574982, 2024). "The results showed that bacterial infection induced increases in the mRNA and protein expression of HYAL 1/2 and CD44 in the E. coli group compared with the NC group." (PMID 29162939, 2017). "Moreover, CD44 ICD may have roles during viral and/or bacterial infections." (PMID 37894408, 2023). "Thus, CD44/HA and TLR4/CD14 could collaborate to diminish bacterial infection." (PMID 25354343, 2014).
hematological malignancies (14 papers, 2014 to 2025). "In contrast to solid tumors, the expression of CD44 standard and variant forms and their functional interplay with HA is less understood in hematological malignancies." (PMID 25941526, 2015). "The correlation between high CD44 expression and a quiescent state suggests that these characteristics may serve as a potential marker to track chemoresistant cells, which is supported by the observation that CD44 is associated with chemoresistance in various hematological diseases." (PMID 39580584, 2025). "Duvelisib-loaded nanoparticles coated with hyaluronic acid have demonstrated their safety and efficacy in models based on CD44-positive cell lines of hematological malignancies." (PMID 39851489, 2025). "A similar role for CD44 has been described for hematological malignancies such as acute lymphoblastic leukemia, acute myeloid leukemia, chronic lymphoblastic leukemia, chronic myeloid leukemia, and multiple myeloma." (PMID 39851489, 2025). "According to the literature, the expression of CD44, a receptor for hyaluronic acid, has been found in many hematological malignancies." (PMID 39851489, 2025). "Lipoic acid-crosslinked hyaluronic acid nanoparticulate drugs appear to offer a more safe and effective treatment for CD44 positive hematological malignancies." (PMID 28958164, 2017). "CD44-directed therapeutic approaches have most intensely been explored in hematological malignancies." (PMID 24684724, 2014). "High CD44 levels have been linked to cell proliferation and tumorigenesis in everything from solid tumors to hematologic malignancies, and siRNA knockdown of CD44 could significantly inhibit tumorigenicity." (PMID 36292918, 2022). "This was unexpected as CD44 has been extensively studied for roles in tumorigenesis, metastasis, and chemo-resistance, in solid tumors as well as hematological malignancies." (PMID 32793603, 2020). "This study provides a proof-of-concept that lipoic acid-crosslinked hyaluronic acid nanoparticulate drugs may offer a more safe and effective treatment modality for CD44 positive hematological malignancies." (PMID 28958164, 2017). "Since CD44 promotes the mobilization of anti-apoptotic mechanisms, it seems to play a negative role in hematological diseases." (PMID 36982699, 2023). "The hyaluronic acid receptors CD44 and the receptor for hyaluronan mediated motility (RHAMM, also known as HMMR and CD168), have been shown to be involved in the pathogeneses of both solid tumors and hematological malignancies." (PMID 35267625, 2022). "Additionally, the development of improved monoclonal antibodies targeting molecules involved in the trafficking of MM, CLL, and ALL cells, such as CXCR4, CD44, SLAMF7/CS1, and CCR9 might open new opportunities for clinical treatments against these hematologic malignancies." (PMID 30787933, 2019).
breast (12 papers, 2017 to 2025). "Overexpression of CD44 has been implicated in early colorectal carcinogenesis, with CD44 knockdown preventing this process." (PMID 29404335, 2017).
gastrointestinal tumors (9 papers, 2011 to 2023). "Earlier studies showed serum CD44 levels in normal individuals is 2.7 nM versus 24.2 nM in advanced gastric and 30.8 colon cancer." (PMID 34599251, 2021). "CD44 and CD133 have regarded as CSCs markers and used as sorting markers for series tumors, including gastrointestinal tumors." (PMID 26769843, 2016). "Overexpression of CD44 has also been shown to potentiate resistance to etoposide by alteration of caspase 9, caspase 3, Bcl-xl, Bak, pRB, and phosphorylation of AKT in colon cancer." (PMID 26079799, 2015). "CD44 and CD133 were extensively investigated and regarded as CSCs markers in a series of tumors including gastrointestinal tumors." (PMID 23874550, 2013).